DEFB108B (defensin beta 108B)
Description:
Has antibacterial activity.
Synonyms: DEFB-8; hBD-8
Tractability: Antibody: UniProt places it where antibodies can reach, with medium confidence; UniProt predicts a signal peptide or a membrane-spanning region; its Gene Ontology location is reachable by antibodies, with medium confidence.
Gene: Protein-coding gene on chromosome 11 (71,833,200 to 71,837,710, forward strand). Ensembl gene ENSG00000184276.
Subcellular location: Secreted
Pathways (Reactome):
Immune System: Beta defensins; Defensins
Gene Ontology:
Molecular function: protein binding
Biological process: innate immune response
Cellular component: extracellular region
Genetic constraint (gnomAD): Loss-of-function variants: 1 observed, 1.4 expected, observed/expected ratio (o/e) 0.72, 90% interval 0.22 to 1.85. That is too few expected variants to judge how well the gene tolerates losing a copy. Missense variants: 82 observed, 65.57 expected, observed/expected ratio (o/e) 1.25, 90% interval 1.04 to 1.5. Synonymous variants: 21 observed, 21.09 expected, observed/expected ratio (o/e) 1, 90% interval 0.7 to 1.43.
Homologues: Orthologues: macaque DEFB108B (93% identical), mouse Defb22 (19% identical), rat Defb22 (16% identical). Paralogues in human: DEFB108C (95% identical), DEFB116 (32% identical), DEFB104A (29% identical), DEFB104B (29% identical), DEFB132 (27% identical), DEFB118 (26% identical), DEFB129 (26% identical), DEFB119 (25% identical), DEFB121 (25% identical), DEFB127 (25% identical), DEFB135 (25% identical), DEFB123 (23% identical), and 7 more.